EGFR (epidermal growth factor receptor)
Diseases named in the same sentence as EGFR in open-access papers (continued):
Sharing a sentence is not in itself a finding about the gene and the disease.
tumor (continued). "The EGFR has been confirmed to be closely related to tumor growth, progression, metastasis, and the poor prognosis of cancer patients, prompting extensive studies on the EGFR signaling pathway." (PMID 34122069, 2021). "The combination of the mAb 4D5 with cetuximab induced a significant decrease in proliferation in the EGFR-dependent colon cancer cell line and an actual regression of the tumours in xenografted mice." (PMID 34663410, 2021). "In EGFR psq-RNAi neoplasia, knockdown of LDH reduces tumor size and prevents neoplastic transformation." (PMID 34240146, 2021). "Previous studies have shown that phosphorylated STAT5 mediate oncogenic effects of EGFR in different tumor tissues." (PMID 34358244, 2021). "Osimertinib (Tagrisso®, AstraZeneca, Cambridge, UK), a tyrosine kinase inhibitor of EGFR, was found to remarkably decrease the tumor size and growth rate in a DLD-1, a colorectal adenocarcinoma cell line, xenograft mouse model." (PMID 33466394, 2021). "A high PD-L1 expression (tumor proportion score, TPS≥50%) and the EGFR L858R mutation were only significantly associated with a better PFS (P <0.05)." (PMID 34888234, 2021). "Analysis of DNA sequences and western blot for EGFR vIII were also performed to assess its role in tumor samples." (PMID 34582442, 2021). "In the present study, we observed that the knockdown of Pgrmc1 led to decreased inflammatory responses in macrophages accompanied by downregulation of EGFR, indicating the tumor-promoting role of Pgrmc1 in macrophages." (PMID 34069911, 2021). "Our results show that the expression levels of SQSTM1 and EGFR proteins are higher in tumor tissues than in the corresponding tumor-adjacent (CTAN) tissues of OSCC patients." (PMID 34830108, 2021). "One possible approach to combine ICI and EGFR TKI therapy more safely would be to target treatments specifically to tumor cells, for example by tumor-homing nanoparticles, thereby bypassing adverse effects due to systemic impact of the drugs." (PMID 34868953, 2021). "Monoclonal antibody therapy is one treatment option for patients suffering from EGFR-related tumor burden." (PMID 34759924, 2021). "Gefitinib, the first FDA-approved anti-EGFR drug, has been shown to prevent autophosphorylation of EGFR in many tumor cell lines and xenografts." (PMID 34234737, 2021). "The activation of EGFR is usually accompanied by upregulation of PD-1/PD-L1 or CTLA-4 to promote tumor immune escape." (PMID 34290608, 2021). "EGFR-TKI therapy combined with a Src inhibitor produces a synergistic antitumor effect against CRIPTO positive/EGFR-mutant xenograft tumor models." (PMID 34568058, 2021). "A high mannose form of EGFR has also been identified as the target of a therapeutic anti-EGFR antibody (A806) in cell lines from distinct tumour types overexpressing the receptor." (PMID 33671245, 2021). "Collectively, our data suggest that CALM1 and EGFR contribute to tumor cell migration and invasion through promoting EMT." (PMID 33602237, 2021). "Despite heterogeneity in IHC interpretation, tumor with EGFR overexpression was correlated with shorter survival in NSCLC." (PMID 34680445, 2021). "Because the PI3K/AKT/mTOR signaling pathway is hyper-activated by the deletion of PTEN, which acts as a tumor suppressor to regulate cell proliferation and cell death, resistance to EGFR-TK inhibitor is increased in MBA-MD-468 cells." (PMID 34681198, 2021). "Intriguingly, EGFR amplification was observed in tumor tissue DNA compared to those in buccal DNA of OSCC patients." (PMID 34298758, 2021). "Fluorescence was correlated with preoperative T1 contrast, tumor size, EGFR expression and other biomarkers." (PMID 34158840, 2021). "Research has ascertained the involvement of suppression of the EGFR/PI3K/Akt/mTOR signaling pathway in the oxymatrine-mediated anti-tumor effects on GBM cells." (PMID 33768139, 2021).
tumor (continued). "A proof-of-concept was derived from HER2-amplified cetuximab-resistant CRC xenograft models where the dual EGFR/HER2 inhibition generated long-lasting tumor regression." (PMID 34202896, 2021). "EGFR is a membrane tyrosine kinase receptor that is known to contribute to the growth activity and tumor survival, and hence this has become a therapeutic target in several cancers." (PMID 33736612, 2021). "In lung tumor, MMP14 was observed to enhance the EGFR signaling to promote tumor metastasis and growth." (PMID 34868395, 2021). "EGFR was reported to be highly expressed in the primary tumor site of NPC, and it is a poor prognosis factor." (PMID 34204797, 2021). "Tumor-targeted ICIs have been investigated, such as EGFR × PD-L1 and CSPG4 × PD-L1, to overcome irAEs induced by the indiscriminate activation of T cells through the PD-1 blockade." (PMID 34358141, 2021). "Our study revealed that interaction of IL-26 and EphA3 in TNBC activates AKT and JNK, leading to tumor proliferation by inhibiting EGFR-TKI-provoked PERK-eIF2α-DDIT3 pathway and ER stress-associated cell death." (PMID 34021125, 2021). "One of the intriguing findings was that there were patients who had a discrepancy between mutant EGFR ctDNA levels and tumor volume." (PMID 34283064, 2021). "Aberrant expression of SDCBP in some cancers has been associated with tumor progression, metastatic dissemination, and poor prognosis via FAK, Src, p38-MAPK, AKT, NFκB, IGFBP2, EGFR, and VEGFR." (PMID 34638436, 2021). "Nevertheless, in MDA-MB-453-based HTM tumors, we found some degree of heterogeneity and EGFR positive tumor areas." (PMID 34070094, 2021). "ST6GAL1 endows resistance of cancer cells to gefitinib (EGFR inhibitor) and trastuzumab (anti-ErbB2 antibody) and also confers tumor cell resistance against hypoxia via enhancing hypoxia-inducible factor-1α (HIF-1α) expression." (PMID 34745942, 2021). "In these neoplasms, EGFR plays a pivotal role in cellular proliferation, the inhibition of apoptosis, angiogenesis, and metastatic progression and chemoresistance." (PMID 33435440, 2021). "A total of 42 somatic hot spot mutations were detected in tumor tissue DNA, and 39 mutations were detected in CTC-DNA, all of which included common changes in PTEN, MET, EGFR, RET, and FGFR3." (PMID 34178679, 2021). "Reciprocally, tumor-associated macrophages highly express CXCR2, HB-EGF, AREG, and ADAM proteinases, but EGFR is only weakly expressed." (PMID 33941851, 2021). "Tumor driver genes (such as TTN, EGFR, and PTEN) showed high mutation rates in the high METTL7B cohort compared with the rates in the low METTL7B cohort." (PMID 34604305, 2021). "As a result, we confirmed that SAE decreased tumor size in a dose-dependent manner and that p-EGFR and cleaved-caspase 3 in tumors were also regulated in a dose-dependent manner." (PMID 34094906, 2021). "SLUG and TAL1 are expressed in the tumor microenvironment by perivascular and endothelial cells, respectively, and to a minor extent, by a fraction of epidermal growth factor receptor (EGFR) -amplified GBM cells." (PMID 34771555, 2021). "For example, autophagy induced by the inhibitors of B-Raf kinase, EGFR, and other receptor tyrosine kinases renders tumor cells resistant to the induction of apoptosis and compromises their antitumor activity." (PMID 33966040, 2021). "The EGF/EGFR signaling pathway was also found to induce EMT in several tumor types, including CRC, through the regulation of E-cadherin expression." (PMID 34147083, 2021). "Results showed enhanced tumor retention of EGFR-targeted SPIONs with minimized systemic exposure, enhanced intra-tumoral SPION distribution via inhalation, and significant inhibition of in vivo tumor growth." (PMID 34299271, 2021). "MRX-2843 also enhanced inhibition of downstream oncogenic signaling in combination with third-generation EGFR TKIs, including osimertinib, resulting in more robust anti-tumor activity both in vitro and in vivo." (PMID 34830794, 2021).
tumor (continued). "As a result, EGFR-specific repebodies exhibited efficient tumor accumulation in a dose-dependent manner and preferential renal clearance, as the primary excretion route for other small-sized proteins." (PMID 33615202, 2021). "EGFR signal generation and, downstream, transduction of Ras/Raf pathway signals contribute importantly to tumor cell progression." (PMID 33827580, 2021). "They show that this approach generates target engagement, T-cell activation, tunable in vivo half-life extension, cellular cytotoxicity dependent on the cell surface levels of EGFR and can inhibit growth of BRAF mutated EGFR-positive tumours in mice." (PMID 33686177, 2021). "We delineate a comprehensive network of IL-9 regulation in Th cells by the interactions among different micro-environmental cues and metabolites with the EGFR-HIF1α signaling cascade and its potential implications in anti-tumor immunity." (PMID 34075041, 2021). "Especially Temsirolimus shows promising anti-tumour activity in HNSCC cell lines with low EGFR expression and also in combination with Carboplatin and Paclitaxel, or Bevacizumab and Cetuximab." (PMID 34944837, 2021). "To date, little is known about the contributions of ChREBP/Mlx to sugar induced-tumor growth in the EGFR hyperplasia model." (PMID 34240146, 2021). "It emphasizes the need for analyses of SR tumor tissues at a multi-omics level for a comprehensive molecular understanding of anti-EGFR SR in CRC." (PMID 34271981, 2021). "The present study investigated the in vivo tumor accumulation of four EGFR-specific repebodies with different binding affinity (KD ranged from 14 nM to 51 pM) by the in vivo near-infrared (NIR) fluorescence imaging in xenograft mouse models." (PMID 33615202, 2021). "Initial investigations revealed that EGFR-mutated NSCLC has lower PD-L1 expression and a low tumor mutational burden (TMB), thus leading to weak immunogenicity." (PMID 34113560, 2021). "High-grade skin toxicity, together to the circulating tumor DNA RAS/BRAF/EGFR wild-type status were the only variables with an impact on PFS and OS." (PMID 34830870, 2021). "Further, Ame55, an anti-EGFR IgG1 antibody, also inhibited tumor growth in a LoVo xenograft mouse model." (PMID 33466394, 2021). "Aberrant EGFR signaling promote tumor cell proliferation, migration and survival thus making it an attractive target for anti-cancer therapy." (PMID 33804477, 2021). "In this model, short-term ablation of LGR5+ cells, in combination with anti-EGFR therapy, elicited a more pronounced inhibition of tumour growth than either treatment alone." (PMID 33673710, 2021). "Copy number gain is detected in around 20% of tumours, while EGFR is overexpressed in around 50% of ESCC tumours and correlates significantly with tumour invasion." (PMID 33169187, 2021). "EGFR is involved in key signaling pathways responsible for the growth, proliferation, migration, and survival of tumor cells." (PMID 34681605, 2021). "Previous studies demonstrate the use of RGD polypeptide, cetuximab, and EGFR (epidermal growth factor receptor) aptamer, all of which have targeted effects on tumor tissues." (PMID 33855009, 2021). "Studies showed that chemo- or radiotherapy induced the nuclear internalization of radionuclide-labelled and unlabeled EGFR, increasing absorbed dose deposited within the tumor." (PMID 34830750, 2021). "In particular, the overactivation of EGFR signaling promotes several hallmarks of tumor onset and progression, such as abnormal proliferation and motility, angiogenesis, and apoptosis inhibition." (PMID 34063168, 2021). "According to the paper’s reports, miR-7-5p can target EGFR and inhibit its expression, and the inhibition of the EGFR/PI3K/Akt signaling pathway can yield the anti-tumor effects on GBM cells." (PMID 33768139, 2021).
tumor (continued). "Specifically, blocking EGFR with mAbs leads to the release of type I interferon (IFN) in keratinocytes, which causes improved antigen presentation in the tumor microenvironment with T cell recruitment." (PMID 34830870, 2021). "GC1118, a novel fully human anti-EGFR IgG1 antibody, exhibited potent inhibitory effects on EGFR signaling, enhanced antibody-mediated cytotoxicity, and significantly inhibited tumor growth in a CRC patient-derived xenograft (PDX) model." (PMID 33466394, 2021). "We also observed that in tumor lysates from the treated mice that the NR4A1-regulated gene products EGFR, cMET, PD-L1, and phosphorylated mTOR were decreased and that these in vivo results complement the in vitro studies in MDA-MB-231 cells." (PMID 34072371, 2021). "Tumor oxygenation responses to EGFR-TKI therapy appear to be mediated via effects on the hypoxia-regulated transcription factor HIF-1α and downstream expression of VEGF." (PMID 34381712, 2021). "In the current study, we found that ILT4 overexpression led to the immunosuppressive TME and tumor promotion in EGFR wild-type NSCLC, rationalizing the synergy of combined ILT4 inhibition with ICI treatment." (PMID 33537094, 2021). "Collectively, these findings suggest that SH003 and DTX inhibit tumor growth by promoting apoptosis and inhibiting the expression of p-EGFR (Y1068) and p-STAT3 (Y705)." (PMID 34445110, 2021). "The concomitant genetic alterations in either tumor suppressor or oncogenic driver genes, or EGFR amplification, were frequently detected in our cohort." (PMID 34663309, 2021). "The observed depletion of tumor-infiltrating B cells also suggests lower TLS development in EGFR-MT." (PMID 34663810, 2021). "In this study, prompted by the observation of the CXCL13 overexpression on certain NSCLC patients, we implemented the strategy to co-express CXCR5 with the anti-EGFR-CAR-T to facilitate T cell migration to the tumor site." (PMID 34553036, 2021). "In order to classify the prognostic role of the primary tumour locations in patients with anti-EGFR treatment, univariate and multivariate analyses were performed." (PMID 34188197, 2021). "EGFR aberrant expression and signaling promotes cell growth, survival, invasion and angiogenesis, and regulates tumor metabolism and cell stemness." (PMID 33918704, 2021). "EGFR is an important therapeutic target for cancer treatment because of its multifunctional role in tumor malignancy." (PMID 34931923, 2021). "Here, we reported the natural product, licochalcone A, exhibited a profound anti‐tumour efficacy through directly targeting EGFR signalling." (PMID 33247550, 2021). "This structure facilitates the simultaneous binding to EGFR on tumor cells and to CD3 on T cells, and effectively induces IS formation." (PMID 34832954, 2021). "PD-L1 can be expressed in tumor cells as a result of genetic modifications including PTEN loss, EGFR mutations, MYC overexpression, mutations in the PI3K/AKT signaling pathway and PDJ amplification." (PMID 33498238, 2021). "EGFR overexpression and tumor hypoxia have been shown to correlate with worse outcome in several types of cancer." (PMID 34381712, 2021). "In vivo, intratumoral injection and convection-enhanced delivery (CED) administrations demonstrated prolonged and favorable tumor retention at 24 h (>50 μg/g for CED in tumor expressing the EGFR), with tumor/brain ratio ≈10." (PMID 33920126, 2021). "Otherwise, the uptake of radioactivity in the tumor appreciably exceeded uptake when compared with other normal organs, thus providing a clear, high-contrast image of an EGFR-expressing xenograft." (PMID 33672373, 2021).
tumor (continued). "This suggests that as tumours establish and develop, EGFR phosphorylation remains dependent on Rac1b expression but alternative mechanisms to activate pERK can be utilised." (PMID 33879799, 2021). "EGFR inhibition has a large impact on the tumor microenvironment through activation of ADCC via NK cells, promoting cross-talk between NK cells and dendritic presenting cells (DC), and priming cytotoxic T cells." (PMID 34298761, 2021). "In this study, we evaluated the correlation between binding affinity and tumor localization of protein binders, called repebody, through near-infrared fluorescence molecular imaging in EGFR-overexpressing tumor xenografts." (PMID 33615202, 2021). "We report here that TMEM52B plays a role in cancer cell invasion and survival, in an EGFR-dependent manner, to reduce tumor growth and early metastasis." (PMID 33641663, 2021). "Our results strongly support the notion that FBXL2 is a tumor suppressor through targeting and promoting EGFR degradation, consequently leading to inhibition of EGFR downstream signaling and suppression of tumor growth." (PMID 34635651, 2021). "In contrast, the number of apoptotic cells significantly increased in both EGFR-high and -low tumor tissues after dasatinib treatment and more so after combination therapy with dasatinib plus cetuximab, as assessed by TUNEL staining." (PMID 32989241, 2021). "Another patient, who withdrew consent on day 37 because of grade 3 mucositis, had an EGFR exon 19 deletion in both ctDNA and tumor DNA (Group B)." (PMID 33270375, 2021). "The results of our validation study, all 6 tumours with + EGFR/− PTEN as determined by MLPA with P105 probemix showed + 7/− 10 in CMA or with additional MLPA methods." (PMID 34257410, 2021). "Next, we investigated the effect of GFHPD consumption and anti-EGFR Ab treatment on the leukocyte marker expression in the splenic compartment that is crucially involved in anti-tumor immune responses." (PMID 34830971, 2021). "Overall, these results demonstrate that hyperosmotic stress contributed to the activation of DPAGT1 and the subcellular translocation of EGFR via NFAT5 induction in the tumor microenvironment." (PMID 32901097, 2021). "Dr. Rosenthal’s group has validated that the tracers bind directly to tumor cells and tumor fluorescence is directly correlated to EGFR expression." (PMID 34002555, 2021). "Nevertheless, it is also important to mention that the overall expression of the EGFR was found to be significantly higher in tumours expressing mutant forms than the wt form of the EGFR." (PMID 35052732, 2021). "Dasatinib treatment, alone or in combination with cetuximab, significantly abrogated the activation of Src in both EGFR-high and -low tumor tissues, compared with that in control tumor tissues." (PMID 32989241, 2021). "On the other hand, in the context of HCC development, the epidermal growth factor receptor (EGFR) modulates relevant aspects of tumor progression such as proliferation, apoptosis, and metastasis." (PMID 34737944, 2021). "Cetuximab, a monoclonal antibody targeting EGFR conjugated with radionuclides showed a therapeutic efficacy in a broad set of tumor types as monotherapy or combination therapy with chemo- or radiotherapy." (PMID 34830750, 2021). "T2-weighted MRI showed enhanced accumulation of targeted nanoparticles in EGFR overexpressing H460 lung tumors and MRgFUS tumor-ablative efficacy (monitored through a series of MRI sequences) was enhanced at lower energy levels, leading to fewer side effects." (PMID 33391494, 2021). "In the current study, an NGS panel targeting exons 18, 19, 20, and 21 of EGFR, and exons 2 and 3 of KRAS was used to compare the mutation status of ctDNA and paired tumor tissue DNA (tDNA)." (PMID 33442424, 2021).